CRP (C-reactive protein)
Diseases named in the same sentence as CRP in open-access papers (continued):
Sharing a sentence is not in itself a finding about the gene and the disease.
COVID-19 (continued). "The meta-analysis indicated that the NAC-treated group of COVID-19 patients had significantly lower CRP levels compared with the placebo group [SMD, −0.32; (95% CI: −56 to −0.09); p-value = 0.0070], although the studies have a high degree of heterogeneity (I2 = 88%)." (PMID 37534078, 2023). "In particular, in COVID-19 patients, a meta-analysis showed that patients with sufficient vitamin D had significantly lower levels of interleukin-6, C-reactive protein, ferritin, lactate dehydrogenase, fibrinogen, and D-dimer compared to those in the vitamin D deficient group." (PMID 36829806, 2023). "The reported improved outcomes in COVID-19 patients with higher levels of inflammatory markers such as suPAR and CRP after treatment with anakinra may therefore reflect favorable impacts of IL-1 blockade on IFN-γ activation and/or IFN-γ effector responses." (PMID 37896812, 2023). "Our analysis included 824 patients admitted to the hospital with COVID-19 who had a CRP determination within the first five days after admission and for whom a BMI value could be calculated." (PMID 38003780, 2023). "CRB-65, CXR and CRP are independent predictors of mortality in COVID-19." (PMID 37760863, 2023). "After adjusting for the covariates in Model 1 plus clinical parameters (BMI, the severity of COVID-19, CRP level, and history of heart failure, malignancy, and psychiatric diseases) (Model 2), the associations remained significant (adjusted OR = 7.54, 95% CI:2.26–25.22, p = 0.001)." (PMID 37968660, 2023). "In addition, there were significant differences between severe and mild COVID-19 patients, especially in CRP, ferritin and total LDH activity." (PMID 38104063, 2023). "Notably, we carried out this retrospective survey involving two different centers recruiting a selected cohort of hospitalized COVID-19 patients free of confounders affecting lymphocyte and neutrophil counts and/or serum CRP values." (PMID 37373750, 2023). "The findings revealed that CRP was the most dominant predictor of mortality within COVID-19 cases." (PMID 37484181, 2023). "Moreover, the mortality of COVID-19 patients with liver injury was significantly influenced by elevated CRP and monocyte counts, as well as reduced lymphocyte counts." (PMID 36902854, 2023). "The present data clearly show that CRP and the other investigated pro-inflammatory biomarkers gradually increase from mild to moderate and/or severe COVID-19 cases and this is supported by an expansion of neutrophils and eosinophils together with a reduction in the lymphocyte count." (PMID 37388734, 2023). "However, our study found that change in CRP during COVID-19 was greater than expected change in comparison to adolescents of the same sex, age, sex, race, and body mass index." (PMID 38136035, 2023). "In our study, NLR was an independent predictor of mortality in obese patients;1 probably because it reflects the inflammatory severity of COVID-19 added to the chronic inflammation of these patients (previously demonstrated by greater levels of IL-6 and CRP in the blood)." (PMID 37024861, 2023). "Finally, we showed a positive correlation of endostatin with soluble disease markers VE-Cadherin, c-reactive protein (CRP), fibrinogen, and interleukin (IL)-6 in our COVID-19 cohort." (PMID 37283766, 2023). "For COVID-19 positive patients, some providers may add CRP, d-dimer, and ferritin to CBC and BMP panels." (PMID 36800930, 2023). "The neutrophil/lymphocyte ratio (NLR), neutrophil count, and LDH, CRP, D-dimer, and ferritin levels were all significantly higher in patients with severe COVID-19 than in those with moderate disease (p < 0.001, p < 0.03, p < 0.001, p < 0.001, p < 0.006, and p < 0.001, respectively)." (PMID 37493737, 2023). "Consequently, nine potential factors were analyzed: obesity; sex; age; day of PE diagnosis (since the onset of COVID-19 symptoms); D-dimer, ferritin, and CRP concentrations; white blood cell (WBC) and platelet (PLT) count; and respiratory index PaO2/FiO2." (PMID 37515199, 2023).
COVID-19 (continued). "In addition, in the MSC and control groups, Zhu (2021) showed CRP variations at baseline and on day 7 in COVID-19 patients only with severe/critical." (PMID 37143167, 2023). "CRP >20 could be the cut-off point separating the healthy population from patients with bacterial pneumonia and COVID-19." (PMID 38585537, 2023). "In the COVID-19 group, a weak significant correlation was found between CRP level and glucose." (PMID 37241176, 2023). "Serum CRP was significantly higher in severe cases of COVID-19 compared to mild cases." (PMID 37363608, 2023). "Recent studies indicate that on one hand, severely elevated CRP and ferritin can worsen clinical outcomes in COVID-19, and on the other hand, a decrease of inflammation parameters throughout the clinical course reduces the risk of development and severity of ARDS." (PMID 37614753, 2023). "CRP levels have been used for predicting COVID-19 disease severity." (PMID 38003780, 2023). "In addition, inflammatory markers such as IL-6 and CRP are also less expressed in COVID-19 patients receiving CP blood transfusion." (PMID 37483597, 2023). "More specifically, an advanced age (≥70 years), elevated levels of leukocytes (≥9.5 × 109/L) and elevated concentrations of CRP (≥90 mg/L), GGT (≥30 U/L), and PCT (≥0.5 ng/mL) at admission were found to be associated with a higher risk for COVID-19 progression to severe disease." (PMID 37363332, 2023). "In this context, CRP may have application as a sensitive serum marker of inflammation and severe infection in COVID-19." (PMID 39263681, 2023). "Additionally, it was found that more children hospitalized with COVID-19 had increased C-reactive protein (CRP) levels compared to those with Flu A." (PMID 38274442, 2023). "However, it was found that more children hospitalized with COVID-19 had increased C-reactive protein (CRP) levels compared to those with Flu A (P < 0.05)." (PMID 38274442, 2023). "In conclusion, an elevated CRP level may be a valuable early marker for predicting the likelihood of disease development in COVID-19 patients with mild symptoms." (PMID 36836429, 2023). "In addition, CRP was found to be the most dominant predicting factor of mortality in moderate-severe COVID-19 patients." (PMID 37484181, 2023). "Furthermore, an elevation in levels of proinflammatory cytokines such as IL-6, serum ferritin, and CRP was observed, with IL-6 serving as a reliable predictor of COVID-19 severity and progression." (PMID 37515156, 2023). "Interestingly, several studies have found that IFNγ-induced protein 10 (IP-10), together with CRP, is a relevant marker of mortality in COVID-19." (PMID 36985262, 2023). "Similarly, in the early phase of the pandemic, the prognostic value of commonly used biomarkers (PCT, CRP, and neutrophils) was investigated in 298 patients with severe COVID-19." (PMID 37510807, 2023). "Other studies demonstrated that NfL concentrations were not correlated with CRP or ferritin, often found to be associated with hyperinflammation in COVID-19 patients, suggesting that the increased NfL concentrations merely reflect enhanced inflammation." (PMID 36769057, 2023). "There was a medium-strength relationship between the level of CRP and anti-S IgG (rs = 0.43), which may indicate a relationship between innate and adaptive immunity factors in COVID-19." (PMID 36975366, 2023). "Statins also reduce C-reactive protein in patients with cardiovascular disease; therefore, they may have potential anti-inflammatory benefits in COVID-19 patients." (PMID 37109231, 2023). "An English study among ER patients with COVID-19, found that MR-proADM could predict 30-day mortality more accurately than CRP, PCT, white blood cell count, and lymphocyte or neutrophil count." (PMID 36941681, 2023). "Moreover, an elevated CRP, alone or in addition to other inflammatory biomarkers, has been proposed as a predictor of COVID-19 severity in previous studies, in agreement with our data." (PMID 37760914, 2023).
COVID-19 (continued). "The alteration of some inflammatory markers, such as D-dimer and C reactive protein and lymphopenia early after SARS-CoV-2 infection, might help identify patients at higher risk of severe COVID-19 and unfavorable outcomes." (PMID 36838277, 2023). "However, some data indicated a greater risk of intracranial hemorrhage after administration of recombinant tissue plasminogen activator (rtPA) in COVID-19 patients with elevated CRP and D-dimer levels, which are commonly increased in COVID-19." (PMID 37231476, 2023). "Among the tested parameters, those positively correlated with comorbid conditions include age, body mass index (BMI), and inflammatory C-reactive protein (CRP), neutrophils, which were shown to be elevated in severe COVID-19 patients, and levels of glucose (fasting and HbA1c)." (PMID 36767932, 2023). "Study participants who consumed more fruits, vegetables and fiber were less likely to develop severe COVID-19, required less corticosteroids and antiviral medication, and had lower inflammatory markers (i.e., CRP) and a significantly shorter length of hospital stay and convalescence." (PMID 37048015, 2023). "In inflammatory diseases like COVID-19, impaired protein synthesis and catabolism leading to sarcopenia are associated with high CRP concentration; however, this relationship is not yet clear." (PMID 37743922, 2023). "Patients with PJP had significantly lower median lymphocyte values (p = 0.033), longer COVID-19 duration (p = 0.014), a higher dose of steroid received (p = 0.026), higher CRP values (p = 0.005), and a lower SARS-CoV-2 vaccination rate than the controls (p = 0.029)." (PMID 37623609, 2023). "Common laboratory abnormalities in COVID-19 patients include leukopenia, thrombocytopenia, increased levels of inflammatory markers such as C-reactive protein (CRP) and cardiac biomarkers, decreased albumin levels, and deviated serum markers of renal and liver function." (PMID 36986138, 2023). "Clinically significantly elevated CRP levels may be an indication for more aggressive treatment of COVID-19." (PMID 36975366, 2023). "This large retrospective study in COVID-19 patients aims to evaluate whether PCT and CRP levels are associated and could help in the identification of secondary bacterial infections acquired during the ICU stay." (PMID 37887237, 2023). "Our study also has some limitations such as a relatively small sample size, lack of data on COVID-19 variants, and no repeat testing for D-dimer, CRP, and coagulation in patients with mild disease." (PMID 37390087, 2023). "When we performed a non-adjusted logistic regression analysis among patients with COVID-19, we discovered that 5 out of 13 predictor variables were significantly associated with IL-6 levels, including ICU admission, CRP, troponin, and severity index (P value < .05)." (PMID 37960722, 2023). "Additionally, STEMI and NSTEMI patients with COVID-19 revealed higher levels of lactate dehydrogenase (LDH) and CRP compared to non-COVID-19 cases." (PMID 37231476, 2023). "The aim of this study is to evaluate the prognostic value of hs-CRP levels at Admission, Discharge, and one-year follow-up in predicting cardiovascular risk among non-diabetic COVID-19 survivors at JIPMER, Puducherry, India." (PMID 37744945, 2023). "COVID-19 patients and smokers’ carriers of one or two copies of the risk allele (rs16969968/A) in CHRNA5 have high ESR and a positive correlation between fibrinogen and C-reactive protein." (PMID 37372959, 2023). "Finally, ROC analysis revealed that low p62 levels discriminated COVID-19 patients from healthy subjects better than the increase in cytokine/CRP levels." (PMID 37174682, 2023). "CRP can be considered as a likely marker of COVID-19 severity." (PMID 37545134, 2023). "Patients with COVID-19 have CRP production as a result of tissue damage and inflammatory cytokines." (PMID 38024833, 2023).
COVID-19 (continued). "In an alternative study, CRP intensity and pulmonary abnormalities observed via CT scan were studied, and the results showed that in the initial phase of COVID-19, elevated CRP levels correlate with both the size of the lung lesion and the extent of disease severity." (PMID 37754237, 2023). "When analyzing the COVID-19 patients age-related (cut-off median = 69 years) by dividing them into an older and younger subgroup, it has been shown that hs-CRP correlated significantly with MCP3 (r = 0.577), CCL23 (r = 0.542) and IL6 (r = 0.722, all p < 0.01) in younger COVID-19 patients." (PMID 37832397, 2023). "C-reactive protein, carbon dioxide, oxygen and glucose are also among the identified immunological and metabolic biomarkers that have a significant importance for early diagnosis and mortality because of COVID-19." (PMID 38014372, 2023). "The moderate form of COVID-19 registered significantly higher values of IL-6, CRP, and IgG." (PMID 36838284, 2023). "A prolonged fever duration and higher PCR test cycle threshold values, WBC levels, and high-sensitivity CRP levels may be indicators of bacterial coinfections in children with COVID-19." (PMID 37144031, 2023). "A previous study has reported that CRP to Lymphocyte Ratio (CLR) and CRP might be better than LYM alone in assessing patients with severe COVID-19 because CLR is a highly sensitive measure to evaluate the severity of COVID-19 in the early phase." (PMID 37089472, 2023). "In the timely identification and anticipation of the severity and fatality of COVID-19, the CRP-to-lymphocyte ratio (CLR) may be a helpful prognostic indicator." (PMID 37197571, 2023). "Another meta-analysis has shown that acute kidney injury and elevated CRP and/or D-dimer levels may be clinically relevant to mortality among patients with COVID-19 who are admitted to hospital." (PMID 36803435, 2023). "Our results are in agreement with other authors whose research shows that high CRP and low albumin values are important for the development of a severe form of the disease, indicating the development of cytokine storms in patients with COVID-19." (PMID 37510752, 2023). "Therefore, high C-reactive protein and erythrocyte sedimentation rate, mechanical ventilation, and ICU admission are also risk factors for liver injury in patients with COVID-19." (PMID 36860673, 2023). "There is another finding that might show a possible interpretation about the effect of the COVID-19 vaccines on CRP." (PMID 37626700, 2023). "Furthermore, CRP concentrations above 80 mg/dl and 100 mg/dl were significantly more prevalent in the bacterial pneumonia group compared to the moderate COVID-19 cases." (PMID 38585537, 2023). "However, the study was adequately powered to detect differences in sleep and CRP from before to during COVID-19 and was strengthened by the use of a within-subjects design and comparisons with demographically and developmentally matched data." (PMID 38136035, 2023). "Previous studies showed elevated CRP in COVID-19 patients following 2–3 months of full recovery." (PMID 36675440, 2023). "ESR, CRP, ASDAS-ESR and ASDAS-CRP were all significant higher after COVID-19 wave than before." (PMID 36611127, 2023). "According to this study, there is an increase in CRP following COVID-19 immunization in patients with inflammatory arthritis, which may indicate that it can cause a disease flare." (PMID 37626700, 2023). "In patients suffering from COVID-19, abnormal values of hematologic parameters (lymphocytopenia), coagulation (D-dimer), and inflammation (especially CRP, PCT, and ferritin levels) are emerging, but according to the authors cited, data are deficient and seem to require validation." (PMID 36900724, 2023). "Clear data such as these are complicated by other findings; higher levels of C-reactive protein (CRP) are associated with the post-acute sequelae syndrome of COVID-19 (PASC), but not with cognition itself." (PMID 37287969, 2023).
COVID-19 (continued). "In addition, CRP levels have been reported to be strongly correlated with the magnitude of myocardial injury in COVID-19 patients." (PMID 37685758, 2023). "Importantly, D-dimer and CRP are considered important prognostic markers and predictors of COVID-19 severity and mortality." (PMID 37228441, 2023). "CRP can be used as a prognostic marker in patients with COVID-19." (PMID 36975366, 2023). "In large clinical studies, CRP has been observed as a key predictor of CVD and all-cause mortality, depression and more recently the need for mechanical ventilation in COVID-19." (PMID 37379302, 2023). "The univariate analysis of the main laboratory parameters revealed a significantly higher frequency of inflammatory syndrome (elevated C-reactive protein, procalcitonin, and ferritin) in the group of patients diagnosed with COVID-19 compared with controls (p < 0.05)." (PMID 37046564, 2023). "LDH and CRP levels may be related to respiratory function (PaO2/FiO2) and may predict respiratory failure in COVID-19 patients." (PMID 37720137, 2023). "A positive correlation (r=0.7 p<0.05) was found between CRP levels and COVID-19 severity." (PMID 37545134, 2023). "Moreover, CRP levels are not only an early stratification marker, but also a valuable tool to predict disease evolution, as higher CRP levels have been detected in COVID-19 progressive patients when compared to stable ones." (PMID 37108262, 2023). "Similarly, in many studies, higher CRP, Fibrinogen, D-dimer, troponin, and procalcitonin levels were reported in severely infected and deceased COVID-19 patients compared to living patients." (PMID 36919085, 2023). "In addition, most COVID-19 patients suffered from lymphopenia (14/16), and all of them show increased levels of C reactive protein and lactate dehydrogenase, which are established markers for the pathology." (PMID 36855168, 2023). "Elevated levels of C-reactive protein have been identified in the serum of COVID-19 patients." (PMID 37111389, 2023). "Pathway analysis identified several immunity-related genes that may link ADHD to COVID-19, including CRP, OXT, IL6, PON1, AR, TNFSF12, and IL10." (PMID 38066446, 2023). "As observed in our results, MSCs significantly reduced the CRP level in COVID-19 patients." (PMID 37365605, 2023). "In line with the cytokine storm hypothesis, several acute phase proteins were elevated in serum of COVID-19 patients, such as CRP, Lipopolysaccharide Binding Protein (LBP), ORM1, and ORM2." (PMID 37739942, 2023). "However, some studies revealed that high CRP levels are also an important indicator of liver injury in COVID-19 patients." (PMID 36671484, 2023). "This is underscored by recent studies in patients with severe coronavirus disease 2019 (COVID-19) in which C-reactive protein (CRP) and soluble urokinase plasminogen receptor (suPAR) plasma levels were successfully used to guide treatment with respectively anti-interleukin (IL)-6 and anti-IL-1." (PMID 36941681, 2023). "We observed that those patients with more risk factors for disease progression and evidence of more severe COVID-19, i.e. older, comorbid, higher CRP, lower lymphocyte count, low oxygen saturations and earlier day of COVID-19 illness, were more likely to require ED reattendance." (PMID 37437035, 2023). "Indeed, the phenomenon of relative insufficiency in AAT functionality is supported by studies that depict high CRP levels accompanied by inadequate AAT responses in severe COVID-19 patients." (PMID 38203593, 2023). "Therefore, lowering the CRP serum level seems to improve the severity and progression of patients with COVID-19." (PMID 37284648, 2023). "Other authors found that post-COVID-19 was strongly associated with the erythrocyte sedimentation rate and C-reactive protein, but not autoantibodies, which suggested an inflammatory rather than autoimmune mechanism of arthritis." (PMID 36837512, 2023).